GAPDH (glyceraldehyde-3-phosphate dehydrogenase)
Diseases named in the same sentence as GAPDH in open-access papers (continued):
Sharing a sentence is not in itself a finding about the gene and the disease.
cancer (continued). "Moreover, it was noted that GAPDH protein level changes in RCC as well in other cancers." (PMID 25225161, 2014). "The mouse mammary gland contains a high percentage of adipocyte as well as the epithelial cells that form cancer, thus, the protein change was normalized by the size of the epithelial cell compartment in the specimen, using cytokeratin, and for protein loading using GAPDH." (PMID 20205934, 2010). "While the Q. infectoria compounds demonstrate promising interaction profiles against specific cancer‐related signaling proteins, the binding affinities of Nyctanthic acid against AKT1 and GAPDH reflect even more favorable energetics in our selected targets." (PMID 40933552, 2025). "Conventional reference genes such as GAPDH, TBP, or miR-16-5p, frequently chosen based on historical usage rather than empirical evidence, show considerable variability in contexts like cancer, metabolic disorders, and biofluids prone to hemolysis." (PMID 41216219, 2025). "GAPDH is a known cancer vulnerability gene, and its depletion in various CRISPR-based viability screens has been observed in different cancer cell lines." (PMID 41175344, 2025). "The opposite relationship between CBD concentration and the expression of caspase-3, LEDGF/p75, and GAPDH is particularly remarkable, especially when considering the role of LEDGF/p75 in cellular stress responses and cancer cell survival." (PMID 41382174, 2025). "Network pharmacology analysis identified AKT1 (serine/threonine protein kinase 1) and GAPDH as key hub genes involved in OC, with AKT1 playing a crucial role in the PI3K/Akt signaling pathway, which is often dysregulated in cancers." (PMID 40933552, 2025). "Furthermore, some studies have indicated that GAPDH expression may be elevated in cancer samples." (PMID 40104395, 2025). "A marked decrease in GLUT-1, HK-I, GAPDH, and LDH, and of Kreb’s cycle and OXPHOS enzymes, supports the likelihood that cancer cells use both glycolysis and OXPHOS, suggesting that metabolism reprogramming is induced by VDAC1 silencing." (PMID 38607066, 2024). "These genes are GAPDH, FSCN1, SLC2A1, FAM83A, PLEK2, and GJB3, some of which have been previously documented in various cancer types." (PMID 38370379, 2024). "For instance, B2M, SLPI, BST2, GAPDH, S100A8, S100A9, and HMGB1, despite their beneficial roles in various infections, they contribute to cancer cell proliferation, invasiveness, reduced survival, and increased disease severity across different cancers." (PMID 38589404, 2024). "Its mechanism of action is largely based on the impairment of the cancer cell energy metabolism by inhibiting HK2 (Hexokinase 2) and GAPDH (Glyceraldehyde 3-phosphate dehydrogenase) resulting in ATP reduction." (PMID 39061250, 2024). "Based on the Warburg hypothesis, which describes the preference of cancer cells for glycolysis over oxidative phosphorylation for energy production, ATP depletion and cell death in response to VC are mainly attributed to reduced glycolysis via inhibition of GAPDH activity by VC-induced H2O2." (PMID 39083898, 2024). "The preclinical experiments have approved the potential of liposomes for downregulating GAPDH and enhancing the efficacy of PTX in cancer chemotherapy." (PMID 38919334, 2024). "Simultaneous production of the somatic form of GAPDH and sperm-specific GAPDS in cancer cells leads to a reorganization of their energy metabolism, which is accompanied by a change in the efficiency of metastasis of certain forms of cancer." (PMID 37711387, 2023). "GAPDH, exchanging glyceraldehyde-3-phosphate (G3P) for 1,3-biphosphoglycerate (1,3-BPG), is essential in aerobic glycolysis of numerous cancers." (PMID 37741973, 2023). "Indeed, the down-regulation of the catalytic subunit of mitochondrial ATP synthase (β-F1-ATPase) is observed in a large number of human carcinomas, either when expressed in absolute levels or normalized relative to other mitochondrial proteins, such as Hsp60 and/or to the glycolytic GAPDH." (PMID 37568591, 2023).
cancer (continued). "The quantitative analysis of the gene expression involves five reference genes (ACTB, TFRC, GAPDH, GUSB, and RPLP0) and 16 cancer-related genes." (PMID 36042999, 2022). "NAD+ is an essential coenzyme that mediates glycolysis, where increased NAD+ levels facilitate the rate of aerobic glycolysis and initiate cancer cells via lactate dehydrogenase (LDH) and glyceraldehyde 3-phosphate dehydrogenase (GAPDH)." (PMID 36556252, 2022). "Seven reference genes (YWHAZ, GNAS, GAPDH, OAZ1, PTMA, B2M, and ACTB) were screened out among the 95 candidate reference genes from the data set of the platelets’ transcriptome of pan-cancer and 73 commonly known reference genes." (PMID 35770000, 2022). "The literature reports several GAPDH inhibitors, that presumably bind at the NAD+-binding site, for potential treatment of various diseases, including parasitic infections and cancers." (PMID 35806451, 2022). "The overall results indicated that GAPDH, B2M, and ACTB were more stable in each cancer than the other four candidate genes." (PMID 35770000, 2022). "The NAD is a major co-enzyme of glyceraldehyde-3-phosphate dehydrogenase (G3PDH) in glycolysis, a major glucose metabolic pathway in cancer cells, and is also involved in tricarboxylic acid (TCA) cycle and oxidative phosphorylation in cancer cells." (PMID 35335372, 2022). "In this regard, GAPDH in glycolysis and OXPHOS have shown therapeutic efficacy restraining the growth of carcinomas." (PMID 35534478, 2022). "GAPDH expression showed the highest fold-change (FC), and STAR had the lowest fold-change among 30 cancer types." (PMID 33917859, 2021). "Elevated levels of NAD+ augment the process of anaerobic glycolysis through glyceraldehyde 3-phosphate dehydrogenase (GAPDH) and lactate dehydrogenase (LDH) and contribute to cancer cell proliferation." (PMID 33609766, 2021). "Based on the 2^-(ddCt) for TERC/GAPDH and MYC/GAPDH from the controls in Group 2, the threshold of cancer detection for these markers was set at 3.12 and 0.155 respectively." (PMID 34790573, 2021). "RNA was then screened by PCR using primers specific for miR-365, as well as matrix metalloproteinase (MMP-2) and a downstream cancer stem cell regulator (NKX2.1), and structural and metabolic standards (beta actin, GAPDH)." (PMID 34204617, 2021). "To obtain an optimal standardization, we first compared the expression level of the four common housekeeping genes GAPDH, β-actin, B2M, and PPIA in twenty selected cancer and normal colon tissue samples." (PMID 33917056, 2021). "It was also isolated from the bacterial culture of T. koningii as a glyceraldehyde 3-phosphate dehydrogenase (GAPDH) inhibitor, suppressing ATP generation in mouse carcinoma FM3A cells." (PMID 34040123, 2021). "We recently showed that inhibiting proton pumps such as MCTs and pH-sensitive glycolytic enzymes such as GAPDH or GPI, reduces the WE phenotype of cancer cells." (PMID 33379345, 2020). "Glyceraldehyde-3-phosphate dehydrogenase (GAPDH), a thiol enzyme involved in catalyzing glycolysis, was identified as a target of polyphenol (–)-epigallocatechin-3-gallate (EGCG) in cancer cells." (PMID 31497592, 2019). "In our study, we propose that the chr12p13 gain leads to the over-expression of genes annotated in this genomic region (i.e., GAPDH, TPI1, FOXM1) creating cancer-specific metabolic addiction." (PMID 30873387, 2019). "The results showed that GAPDH protein as well as mRNA were downregulated in combination 2-DG–NDV-treated AMN3 and AMJ13 cancer cells compared with the untreated control cells." (PMID 31612140, 2019).
cancer (continued). "Furthermore, we summarize the molecular mechanisms and the cellular effects of GAPDH aggregates, which are correlated with mitochondrial malfunctions and can be considered a potential therapeutic target for various diseases, including cancer and neurodegenerative disorders." (PMID 31027346, 2019). "The model was used to investigate how changes in extracellular glucose and lactate influence cancer bioenergetics through GAPDH and LDH flux, predicting that GAPDH and LDH are most sensitive to glucose and lactate respectively." (PMID 30496306, 2018). "For instance, malonylation on K184 of glyceraldehyde 3-phosphate dehydrogenase (GAPDH) regulates the activity of this key metabolic enzyme, whereas several Kmal sites in histone proteins have potential connections with cancer." (PMID 30639696, 2018). "Further, consistent with the model, the strategy is selective for cancer cells, as there were only very modest effects of hypoxia, MCT1/2 inhibition, and knockdown of GAPDH or GPI on the survival of normal MCF10A breast epithelial cells." (PMID 30065243, 2018). "Across the different conditions and cells, the predicted selective and pH-specific targets GAPDH, GPI, and ACAT2 achieved the largest detrimental effect on cancer cell survival." (PMID 30065243, 2018). "We then systematically identify metabolic targets (GAPDH and GPI) with predicted amplified anti-cancer effects at acidic pHi, forming a novel therapeutic strategy." (PMID 30065243, 2018). "However, the mechanism behind MG mediated inhibition of GAPDH activity in cancer cells is unknown." (PMID 26911935, 2016). "With P-gp and glyceraldehyde 3-phosphate dehydrogenase (GAPDH) as a model, the proposed ECL assay was successfully employed to monitor the drug resistance of cancer cells." (PMID 28451145, 2016). "GAPDH interacts with an alternatively spliced isoforms of pyruvate kinase, PKM2 and GPI in cancer cells." (PMID 26911935, 2016). "However, the roles of adducted GAPDH in cancer cells remains unclear." (PMID 25859407, 2015). "However, these cancer-related mechanisms involved in GAPDH regulation remain unclear." (PMID 25859407, 2015). "Both major consumers (LDHA, FASN) and producers (GAPDH, MTHFD and MDH2) of NAD(P)H are subject of major research efforts as drug targets against cancer." (PMID 25621879, 2015). "S-nitrosylation and nuclear translocation of GAPDH can be blocked by overexpressed glutaredoxin and CGP3466B (a drug) in non-cancer cells." (PMID 25859407, 2015). "In these subnetworks, different RNAs are located on PCSRs including GAPDH, ZEB2, mir-20b, mir-21, mir-141 and mir-200c supporting the important effects of these RNAs and their regions in cancer." (PMID 24796549, 2014). "Expression of genes within the glycolytic pathway (GAPDH, TPI1 and GPI) remained highly correlated in both in NSCLCs and non-cancer control tissue samples." (PMID 23620736, 2013). "Several glycolytic enzymes, for example glyceraldehyde 3-phosphate dehydrogenase (GAPDH) and pyruvate kinase M2 (PKM2), have been reported overexpressed in cancer." (PMID 24252137, 2013). "The potential reference genes GAPDH, HPRT1, and RPLP0 were measured in all samples from NSCLC patients and cancer-free controls." (PMID 24313945, 2013). "Expression levels, carbonyl levels and enzyme activity of GAPDH in controls (CTR), dysplastic (DYS) and carcinoma tissues (SCC) are reported." (PMID 22470562, 2012). "We examined, in addition to ACTB and GAPDH, four other reference genes, HPRT1, RPL29, 18S rRNA, and B2M that have been evaluated as reference genes in recent studies for other human cancers." (PMID 20507635, 2010).
cancer (continued). "In comparison, in this study, the average expression levels of GAPDH and RPL29 were similar in stomach tissues and cancer cell lines." (PMID 20507635, 2010). "A review on the selection of normalizers for RT-qPCR cancer studies recommended that a combination of PPIA and ACTB, HPRT1 (hypoxanthine phosphoribosyltransferase 1), TBP (TATA-binding protein), or GAPDH, or an appropriate combination of three of these genes, should be employed." (PMID 40943534, 2025). "To address this question, we studied GAPDH heme transfer to the client protein indoleamine 2,3-dioxygenase 1 (IDO1), whose enzyme activity is heme-dependent and regulates mammalian immune responses and cancer progression." (PMID 40609793, 2025). "This is because malignant tumors rely largely, if not entirely, on the Warburg effect, where the role of GAPDH in aerobic glycolysis is basic." (PMID 40943534, 2025). "For instance, in Glycolysis/ Gluconeogenesis and Biosynthesis of amino acids pathways, lysine 131 (K131) site of PGK1, K322 and K13 sites of ALDOA, K215 and K194 sites of GAPDH, K89 site of ENO1, K678 site of PFKM were hyper-lactylated in cancer cells and tissues." (PMID 40849487, 2025). "GAPDH was not investigated as a suitable candidate until 2002, when GAPDH mRNA levels were found to be higher in some cancers but lower or unaltered in others in comparison to normal tissue and, therefore, an unsuitable reference gene for RNA analysis." (PMID 40018301, 2025). "No statistical difference in GAPDH expression levels was detected between Type I and Type II cancers." (PMID 40943534, 2025). "Several GAPDH-derived peptides were shown to enhance resistance to DNA damage in Saccharomyces cerevisiae cells or exhibit antimicrobial activity while the GDA10-3 peptide specifically shows anti-cancer properties by inhibiting cell proliferation." (PMID 41006687, 2025). "The finding that some cancer cells exhibit a more oxidized NAD+/NADH ratio upon serine starvation is surprising, particularly when increased serine synthesis will result in a higher demand for NAD+ to support increased flux through GAPDH and PHGDH." (PMID 40654753, 2025). "GAPDH demonstrates both enzymatic and non-enzymatic functions, with both being intricately involved in cancer progression, invasiveness, and metastasis." (PMID 38611852, 2024). "Five enzymes involved in glycolysis present only or mainly in sEVs isolated from cancer-derived cell lines were validated: aldolase (ALDOA), glyceraldehyde-3-phosphate dehydrogenase (GAPDH), phosphoglycerate kinase (PGK1), enolase (ENO) and pyruvate kinase (PKM)." (PMID 37189694, 2023). "Although many studies have warned that the widely used GAPDH is not stable and should not be used as a reference gene in cancer research, thousands of papers each year still use it without validation." (PMID 37274277, 2023). "Copy counts for nucleus‐derived sequences of GAPDH and B4GALNT1 were significantly higher in the AH from patients with progressive disease, compared to the AH from progression‐free patients and control non‐cancer patients." (PMID 36148636, 2023). "Many other proteins thought to be highly abundant in EVs also did not have a pan-cancer expression, including GAPDH, HSPD1, and ENO1." (PMID 36470535, 2023). "The substance is an oxathiazinane (tetrahydro-1,4,5-oxathiazin-4,4-dioxide) and has inhibitory effects on glyceraldehyde 3-phosphate dehydrogenase (GAPDH) expression and activity, selectively resulting in oxidative stress, mitochondrial dysfunction, and programmed cell death in cancer cells." (PMID 37895015, 2023). "Expression of other members of RQC including Pelota, SMG1 did not correlate across cancer types, nor were patterns observed in the expression of reference genes (GAPDH, HNRPL, PCBP1, SNW1, and RER1) identified to have stable expression patterns in human cancer and matching normal cell types." (PMID 38140537, 2023).
cancer (continued). "Non-glycolytic functions of GAPDH including the regulation of cell death, autophagy, DNA repair, and RNA export were observed in physiological and pathological conditions such as cancer and neurodegenerative disorders." (PMID 35268705, 2022). "While we did not evaluate the level of autoantibodies against KCNAB2 and GAPDH in sera of other types of cancer, referring to published results of screening autoantibodies based on proteome microarrays for a variety of tumors, autoantibodies against KCNAB2 and GAPDH seems to be specific in ccRCC." (PMID 36789694, 2022). "Our data show that selected 3-bromo-isoxazoline derivatives are able to penetrate cancer cells and to bind and inhibit the GAPDH enzyme altering the cancer metabolic profile and decreasing cancer-cell growth, without affecting normal cells." (PMID 35804925, 2022). "GAPDH interacts with active AKT, sustaining enzyme activity; thus, this protein may be a crucial regulator of cancer cell functions and a marker of cancer cell progression and prognosis." (PMID 36362243, 2022). "However, we did not observe any significant changes in the amplification of nuclear genes, GAPDH (p = 0.1543) and ACTB (0.5629), in the serum EVs DNA from PDAC and non-cancer subjects." (PMID 36323735, 2022). "We also added a commonly used reference gene in cancer studies, GAPDH, and a randomly selected non-reference gene, HEY1, for a total of 14 pan-cancer candidate reference genes." (PMID 34422018, 2021). "HSP90 was used as a control because GAPDH, cyclophilin A, and vinculin (data not shown) were increased under hypoxia in cancer cells." (PMID 34824343, 2021). "It is interesting to note that our results agreed with other reports, where it was also found that the GAPDH gene is not the most suitable for use as an internal control gene in cancer studies." (PMID 34573317, 2021). "However, ACE2/GP2 (R 0.108 in normal and R −0.045 in cancer) and FURIN/GAPDH (R −0.198 in normal and R 0.023) present differential correlations between normal and cancer samples." (PMID 33796097, 2021). "Secondly, a cancer-associated D1425N mutation of CSB, which sensitizes cells to cisplatin, does not affect RNAPII occupancy at PPP sites of ACTB, GAPDH and RPL13A genes." (PMID 33806087, 2021). "This indicates that GAPDH is not an attractive target in anti-cancer therapy and emphasizes the importance of proper choice of housekeeping genes for correct interpretation of experimental results." (PMID 32252351, 2020). "GAPDH and ACTB were identified as cancer essential genes more often by CES than by other methods at the given ranking thresholds, resulting in the largest AUC for both genes (96.5% and 97.9% for GAPDH and ACTB, respectively)." (PMID 31732481, 2019). "Non-glycolytic functions of GAPDH include the regulation of cell death, autophagy, DNA repair and RNA export, and they are observed in physiological and pathological conditions as cancer and neurodegenerative disorders." (PMID 31027346, 2019). "Although GAPDH can be deregulated in tumor cells, there is still no perfect internal reference that remains totally unchanged in cancer cells." (PMID 31662805, 2019). "However, multiple published studies have used different genes (e.g., KRAS, BRAF, APP, ACTB, GAPDH, 16s rRNA, ALU, LINE 1) as biomarkers to determine cfDI in various cancers." (PMID 31620364, 2019). "The expression profile of NKILA was detected in 137 paired ESCC cancer tissues and corresponding noncancerous tissues using qPCR assays, while GAPDH was used as the normalization control." (PMID 29348395, 2018). "This analysis identified GAPDH (glyceraldehyde 3-phosphate dehydrogenase) and its paralog GAPDHS, which catalyze the sixth step (and a principal junction) of glycolysis, as strong modulators of cancer pH-dependent metabolism." (PMID 30065243, 2018).